BSCL2 (BSCL2 lipid droplet biogenesis associated, seipin)
Diseases named in the same sentence as BSCL2 in open-access papers (continued):
Sharing a sentence is not in itself a finding about the gene and the disease.
type 2 diabetes (2 papers, 2021 to 2023). "CGL2 patients with biallelic null mutations in BSCL2 suffer from early premature aging signs, including regional atrophy of subcutaneous tissues, as well as cardiovascular lesions, type 2 diabetes and psychomotor abnormalities." (PMID 36715159, 2023). "In addition, BSCL2/seipin deficiency has been shown to induce ER stress, a process that has also been implicated in altered innate immunity and myeloid cell dysfunction in type 2 diabetes and atherosclerosis." (PMID 33498782, 2021).
adenovirus infection (1 paper, 2020). "We used adenovirus to express GFP (control) or Bscl2/GFP in the SVF cells, and Seipin protein levels were substantially elevated by the Bscl2‐adenovirus compared to GFP‐adenovirus infection." (PMID 33304767, 2020).
B-cell lymphoma (1 paper, 2020). "The BSCL2 and SETX VUS variants have been previously reported in B-cell lymphoma and cancer patients, respectively." (PMID 32397312, 2020).
Brain atrophy (1 paper, 2016). Partial or complete wasting (loss) of brain tissue that was once present. "There is a tendency for a reduction in brain volume in patients with BSCL2 mutations, but that does not seem to be due to brain atrophy." (PMID 26985241, 2016).
Charcot-Marie-Tooth disease (1 paper, 2015). An inherited degenerative disorder involving the peripheral nerves. "Dominant mutations in the BSCL2 gene, encoding the ER-resident protein seipin, are found in families presenting with a broad range of neurological features, including HSP with amyotrophy (SPG17), and Charcot Marie Tooth disease." (PMID 25875445, 2015).
dyslipidaemia (1 paper, 2026). "Regarding lipid metabolism, dyslipidaemia was particularly pronounced in the patient with BSCL2‐related disease, consistent with the established role of seipin in lipid droplet biogenesis and hepatic lipid turnover." (PMID 41466769, 2026).
Epileptic encephalopathy (1 paper, 2026). A condition in which epileptiform abnormalities are believed to contribute to the progressive disturbance in cerebral function.
Myocardial fibrosis (1 paper, 2022). "The BSCL2 deletion‐induced cardiac dysfunction was not accompanied by abnormal cardiomyocyte morphology and excessive myocardial fibrosis (assessed by trichrome staining) in hearts of Bscl2cKO mice." (PMID 35384404, 2022).
pancreatic cancer (1 paper, 2021). "Among 39 differentially expressed factors, seven up-regulated genes (CAV2, CIDEC, HILPDA, HSD17B11, NCEH1, RAB5A, and SQLE) and two down-regulation genes (BSCL2 and FITM1) were significantly associated with overall survival of pancreatic cancer patients." (PMID 34078402, 2021). "We further identified that enhanced expression of 7 genes namely CAV2, CIDEC, HILPDA, HSD17B11, NCEH1, RAB5A, and SQLE are associated with significantly shorter overall survival whereas elevated expression of BSCL2 and FITM1 correlates with longer overall survival of pancreatic cancer patients." (PMID 34078402, 2021).
polyneuropathy (1 paper, 2019). A disease or disorder affecting more than one nerve. "Cognitive disabilities and polyneuropathy are features associated exclusively with clinical CGL type 2 arising from seipin (BSCL2) gene mutations." (PMID 30563316, 2019).
schizophrenia (1 paper, 2025). A major psychotic disorder characterized by abnormalities in the perception or expression of reality.
Telangiectasia (1 paper, 2020). Telangiectasias refer to small dilated blood vessels located near the surface of the skin or mucous membranes, measuring between 0.5 and 1 millimeter in diameter. "The second DNA damage reporter Bscl2 is associated with DNA replication and activation of the ATR (ataxia telangiectasia and Rad3-related) DNA damage signalling pathway." (PMID 31935871, 2020).
Umbilical hernia (1 paper, 2019). Protrusion of abdominal contents through a defect in the abdominal wall musculature around the umbilicus. "In addition, umbilical hernia, present in our patient at three months, was reported to be associated only with BSCL2 mutations in one patient." (PMID 30563316, 2019).
metabolic disease (11 papers, 2013 to 2025). A congenital disorder (due to inherited enzyme abnormality) or acquired (due to failure of a metabolically important organ) disorder resulting from an abnormal metabolic process. "We examined whether systemic adeno-associated virus delivery of human BSCL2 could reverse metabolic disease in seipin knockout mice, where white adipose tissue is absent." (PMID 36320417, 2022). "Given the critical role of the liver in glucose regulation, we speculated that intact hepatic Bscl2 expression may protect adipose tissue-specific Bscl2-deficient mice from metabolic disease." (PMID 31848133, 2020). "Our data raise the possibility that adipose tissue-specific ablation of Bscl2 alone may be insufficient to cause all features of the severe metabolic disease observed in congenital seipin deficiency, at least in mice." (PMID 29459250, 2018). "OXCT1 deficiency also explains the ketosis seen in FRDA patients carrying BSCL2 variants when exposed to a high fat diet, and emphasizes the features of FRDA as a specific metabolic disorder in addition to being a disorder of mitochondrial function." (PMID 36016708, 2022). "We tested this approach with metabolic disease genes expressed in adipocytes, identifying and subsequently validating novel interactions between BSCL2 and PLIN1 (protein–protein) as well as CEBPA and AGPAT2 (genetic regulatory)." (PMID 30940487, 2019). "Previous reports indicate that hepatic Bscl2 deficiency does not play a significant role in the development of metabolic disease in SKO mice." (PMID 39069561, 2024). "Both BAT development and browning of residual EWAT are also evident in Bscl2 knockout mice but do not prevent overt metabolic disease, suggesting that other mechanisms must underlie this difference." (PMID 29459250, 2018). "While there is evidence that overexpressing Bscl2 in the liver may be beneficial in high-fat diet fed mice, the literature indicates that hepatic Bscl2 deficiency does not play a significant role in the development of metabolic disease in SKO mice." (PMID 39069561, 2024). "Therefore, the presence of hepatic Bscl2 in our adipose tissue-specific model might provide protection from the development of metabolic disease." (PMID 31848133, 2020). "To investigate whether thermogenesis was offering any protection from metabolic disease, we examined whether housing male Ad-B2(−/−) mice at thermoneutrality would uncover the metabolic phenotype observed in global Bscl2 knockout mouse models, which typically have used male mice." (PMID 31848133, 2020). "Thus, dietary restriction or manipulation in BSCL2 patients may have beneficial effects in alleviating metabolic disorders." (PMID 24358199, 2013). "Seipin/BSCL2 has been identified as the pathogenic gene for Berardinelli-Seip congenital lipodystrophy type 2 (BSCL2) and induces the most severe form of lipodystrophy, characterized by an almost complete absence of adipose tissue and associated metabolic disorders." (PMID 35185590, 2022). "Metabolic disease also failed to manifest in adipose-tissue-specific Bscl2 KO mice when hepatic Bscl2 was additionally ablated using AAV to deliver Cre recombinase to the liver." (PMID 36320417, 2022). "Female Ad-B2(−/−) mice housed at thermoneutrality and fed a chow diet failed to develop the metabolic disease observed in global Bscl2 knockout mice." (PMID 31848133, 2020).
infection (8 papers, 2011 to 2025). The state of being infected such as from the introduction of a foreign agent such as serum, vaccine, antigenic substance or organism. "It is less clear why infections are linked to BSCL2 deficiency, but a direct effect in macrophages is credible." (PMID 33498782, 2021). "Therefore, it is unlikely that BSCL2 deficiency in the myeloid lineage per se significantly contributes to an increased risk of infection in CGL2 patients." (PMID 33498782, 2021). "Overall, our findings reveal that selective Bscl2 deficiency in macrophages does not critically impact the innate immune response to infection." (PMID 33498782, 2021). "A recent study identified infection as a major cause of death in CGL2 patients, leading us to examine whether Bscl2 loss could directly affect the innate immune response." (PMID 33498782, 2021). "Patterns of DEGs in MDM of homozygotes with either the BSCL2 or AGPAT2 mutations clustered together and separately from WT control samples, regardless of their infection status." (PMID 38755198, 2024).
genetic disorder (5 papers, 2020 to 2025). "Mouse models deficient in Bscl2 almost entirely reproduce this phenotype, providing a valuable in vivo tool to investigate and characterise this rare genetic disorder." (PMID 31848133, 2020).
neurological disorders (5 papers, 2012 to 2024). "The resident endoplasmic reticulum protein, seipin, encoded by the BSCL2 gene, has been implicated in both metabolic and neurological disease." (PMID 23049863, 2012). "Seipinopathy is designated as a spectrum of neurologic diseases caused by BSCL2 mutations." (PMID 26815532, 2016).
cancer (2 papers, 2018 to 2020). A tumor composed of atypical neoplastic, often pleomorphic cells that invade other tissues. "BSCL2 may also play a tissue‐autonomous role in controlling lipid storage in adipocytes and in preventing ectopic lipid droplet formation in non‐adipose tissue, among others in cancer cells." (PMID 29266765, 2018).
kidney disease (1 paper, 2018). "Adipose tissue transplant partially rescued renal function in Bscl2 knockout mice, indicating that loss of adipose tissue was at least partly responsible for kidney disease in these mice." (PMID 30552349, 2018).
neurodegenerative disease (1 paper, 2018). A disorder of the central nervous system characterized by gradual and progressive loss of neural tissue and neurologic function. "Notably, a group of neurodegenerative diseases is associated with the presence of missense mutations in BSCL2 (associated with protein’s function improvement)." (PMID 29329523, 2018).
tumor (1 paper, 2020). "Low expression of FITM1, ABCG5, BSCL2, and GPAM in non-viral HCC tumor specimens generally predicted worse survival status." (PMID 32174969, 2020).
BSCL2 also shares sentences with these, for which no sentence is quoted: Progressive encephalopathy (7 papers); partial lipodystrophy (3); cardiac hypertrophy (2); familial partial lipodystrophy (2); acquired lipodystrophy (1); atherosclerosis (1); Azoospermia (1); bone cysts (1); Brown-Vialetto-Van Laere syndrome (1); CANDLE syndrome (1); Charcot-Marie-Tooth disease type 2 (1); Charcot-Marie-Tooth neuropathy type 2 (1); cognitive decline (1); congenital generalized lipodystrophy (1); distal motor neuropathy (1); distal muscular atrophy (1); dyslipidemia (1); Dystonia (1); epilepsy (1); Frasier syndrome (1); hearing loss (1); heart failure (1); Hirsutism (1); Hypercholesterolemia (1); hyperlipidemia (1); Hypertension (1); Hypoglycemia (1); infectious disease (1); intrauterine growth restriction (1); juvenile amyotrophic lateral sclerosis (1).
A further 16 diseases each share a sentence with BSCL2 in 1 paper.